CAT (catalase)
Diseases named in the same sentence as CAT in open-access papers (continued):
Sharing a sentence is not in itself a finding about the gene and the disease.
colorectal cancer (36 papers, 2011 to 2026). A primary or metastatic malignant neoplasm that affects the colon or rectum. "In this study, key antioxidant enzymes, including catalase and superoxide dismutase, which neutralize reactive oxygen species, were diminished in colorectal cancer patients compared to healthy individuals." (PMID 41596358, 2026). "The findings concurred with a previous study that demonstrated reduced activity of the antioxidant enzymes catalase and superoxide dismutase in colorectal cancer, indicating a compromised antioxidant defense mechanism." (PMID 41596358, 2026). "Previous studies have demonstrated that MZLAE reduces lipid peroxidation by reducing malondialdehyde (MDA) levels and increasing enzyme antioxidant (catalase) levels in HT-29 colorectal cancer cells." (PMID 39290583, 2024). "Quercetin suppresses the expression of critical antioxidant enzymes, such as Nrf2/HO-1, GPX, SOD, and CAT, in both 5-FU-resistant colorectal cancer cells and cisplatin-resistant ovarian cancer cells." (PMID 39164783, 2024). "It has been reported that resveratrol synergizes with 5-FU to combat colorectal cancer, increasing the ROS levels and decreasing the CAT and GPX levels." (PMID 39164783, 2024). "In contrast, CAT activity was considerably lower in the serum of patients with colorectal cancer compared to the control group." (PMID 37107276, 2023). "Our findings demonstrated that patients with colorectal cancer have higher levels of oxidative damage biomarkers and antioxidant activity, except for CAT, compared to healthy controls." (PMID 34381561, 2021). "Although the role of catalase in tumor is contradictory, some authors reported an increase of catalase levels in colorectal cancer." (PMID 34943833, 2021). "Extracts’ ability to activate antioxidant enzymes (superoxide dismutase (SOD) and catalase (CAT)) was evaluated on human colorectal carcinoma cells (HCT116)." (PMID 34439431, 2021). "Our analysis using the UALCAN database, however, showed that CAT expression was more variable in pancreatic and colorectal carcinoma patients, while the NFE2L2 expression was very similar between the three types of tumors." (PMID 33540681, 2021). "In the UALCAN analysis, a similar CAT expression among pancreatic carcinoma, colorectal carcinoma, and glioblastoma patients was observed." (PMID 33540681, 2021). "We demonstrated significantly higher SOD and CAT activities in colorectal cancer tissue compared to normal mucosa (p < 0.0001, p < 0.0001, respectively)." (PMID 32575703, 2020). "Genetically modified LAB expressing antioxidative enzymes (SOD or CAT) showed an anticancer effect in a rodent model of colorectal cancer." (PMID 30680175, 2019). "SOD activity was significantly higher, whereas CAT activity was considerably lower in the serum of patients with colorectal cancer compared to the control group (p < 0.0001, p < 0.0001, respectively)." (PMID 31652642, 2019). "In present study we investigate the possible association between polymorphisms of superoxide dismutase 1 (SOD1, OMIM: 147450) and catalase (CAT, OMIM: 115500) genes and the risk of colorectal cancer (CRC)." (PMID 28775994, 2017). "Nuclear localization and post-translational modifications of p27Kip1 were also demonstrated by catalase treatment of colorectal carcinoma and neuroblastoma cells, extending our findings to these other human cancer types." (PMID 22970236, 2012). "Studies on colorectal cancer, urothelial bladder carcinoma and ovarian cancer have similarly demonstrated a decrease in both CAT and SOD." (PMID 21871117, 2011). "The changes also were associated with a reduction in levels of glycoproteins and antioxidant enzymes such as SOD, catalase, and GSH, which may cause colorectal cancer and is linked with impairment in the integrity of the intestinal barrier." (PMID 40063073, 2025).
colorectal cancer (continued). "In the case of our study on colorectal cancer cell lines, we observed a decrease in CAT enzyme activity after administration of EB5 and cisplatin compared to betulin, which caused a slight increase in CAT activity in the case of the RKO line." (PMID 39195258, 2024). "Depending on the colorectal cancer staging, a decrease or increase in catalase levels is observed." (PMID 39195258, 2024). "As a result, we explored the influence of NaSH on SpCAT in colorectal cancer cells and M17 human neuroblastoma cells treated with rotenone, which should allow discriminating between a temporarily (CAT–Fe(IV)=O) and an irreversibly (CAT–Fe(III)–sulfheme) inactive state of the enzyme." (PMID 27848965, 2016). "CAT expression in the rest of pancreatic carcinoma (IMIM-PC-2 and RWP-1), colorectal carcinoma (HT-29, SW-480, and SW-620) and glioblastoma (HGUE-GB-18, HGUE-GB-37, HGUE-GB-39, and HGUE-GB-42) cell lines were more than 80% lower than that observed in Hs766T." (PMID 33540681, 2021). "Among these products, H2O2, a potent pro-oxidant, is particularly toxic, and for this reason we have suggested DAO in combination with CAT as therapeutic enzymes to improve the therapy of IBD and to prevent the colorectal cancer." (PMID 28108908, 2017). "This study evaluated esketamine's effects on serum biomarkers of oxidative stress (glutathione, catalase, malondialdehyde, superoxide dismutase), inflammatory mediators (TNF-a, CRP IL-6), and T lymphocyte subsets in patients undergoing laparoscopic colorectal cancer resection." (PMID 40951888, 2025). "In the most recent study on SOD dichotomy, researchers evaluated the levels of Mn-SOD, CuZn-SOD, and other antioxidant enzymes such as CAT and GPx in both tumors and adjacent non-tumor tissue from colorectal cancer patients." (PMID 38891864, 2024). "Markers such as CAT, AOPP, H2O2 and MDA could represent non-invasive oxidative stress markers in colorectal cancer." (PMID 37107276, 2023). "Moreover, it can downregulate catalase and GPx expressions and upregulate MDA, SOD, and LPO levels in colorectal cancer cells." (PMID 35366874, 2022). "Besides, it was found that resveratrol combined with 5-FU chemotherapeutic drug against colorectal cancer synergistically increased the generated ROS, LPO, and SOD levels and decreased the catalase and GPx levels." (PMID 35366874, 2022). "The effect of the nontoxic microgreen extracts on the activities of SOD and CAT antioxidant enzymes was measured in HCT116 human colorectal carcinoma cells and compared against non-exposed cells." (PMID 34439431, 2021). "In agreement with previous studies, lower activities of GPx and CAT as well as higher activities of SOD were observed in patients with oesophageal, gastric, and colorectal cancers compared with control subjects and low NQO1 activity was linked to increased risk of acute leukemia." (PMID 27057281, 2016). "Colorectal cancer is characterized by increased MnSOD expression (in vitro studies) and SOD expression while CAT, GPx, and GR are decreased (in vivo study); and finally, (iii) SOD, CAT, and XOR are proposed as prognostic markers in cancer of the lung, bladder, ovarian, and colon." (PMID 34822465, 2021).
infertile (36 papers, 2007 to 2025). "Catalase enzyme activity (CAT) was demonstrated to be associated with low sperm quality, and one study reported that CAT-262T/T genotype was negatively associated with infertility in idiopathic infertile males." (PMID 26618172, 2015). "It was further mentioned that the total antioxidant capacity (TAC) and the catalase (CAT) levels were significantly elevated in fertile compared to infertile groups." (PMID 38792459, 2024). "When compared to the proliferative phase, proteomic studies of EVs from the uterine fluid of fertile and infertile women revealed an enrichment of proteins linked to invasion (LGALS1/3, S100A4/11) and implantation (PRDX2, IDHC, CAT, ANXA2) in secretory phase." (PMID 37899459, 2023). "CP causes infertility by inducing oxidative stress via inducing an increase in the malondialdehyde (MDA) levels and reducing superoxide dismutase (SOD) and catalase (CAT) activity and glutathione peroxidase (GPx) levels in the testes." (PMID 36698735, 2023). "The genotype frequencies of UCP2 G-866A, MnSOD C47T, and CAT C-262T were found to be significantly different among the fertile subjects (control group), infertile subjects with more than 50% motility, and infertile subjects with less than 50% motility." (PMID 34527175, 2021). "This study was designed for investigating the mRNA expression levels of the antioxidant genes NRF2, GPX4, SOD2, and CAT in infertile males before and after treatment with DPP and healthy controls." (PMID 34401649, 2021). "The genotype frequencies of UCP2 G-866A, MnSOD C47T, and CAT C-262T were found to be significantly different among the fertile subjects, the infertile subjects with more than 50% motility, and the infertile subjects with less than 50% motility." (PMID 34527175, 2021). "Yet, another study described that SOD and CAT activities were correlated with sperm concentration, both being enhanced in subfertile/infertile men." (PMID 34573073, 2021). "In fact, the activity of catalase was significantly greater in the group of drivers and the group of infertile patients with varicocele than in the control group." (PMID 32899311, 2020). "Even though other authors reported a decreased CAT activity in infertile patients with varicocele, the results of this study are similar to those obtained in a previous research of ours." (PMID 31781347, 2019). "Thirteen studies were included in the meta-analysis with 740 infertile patients and 263 fertile controls to analyze the catalase activity in seminal plasma." (PMID 29849956, 2018). "In other analogous studies, unchanged, elevated, and decreased activities of SOD, CAT, and GPx were found in semen of infertile males compared to the fertile controls." (PMID 30116493, 2018). "Seminal plasma levels of catalase were significantly lower in infertile patients while the levels of free 8-iso-PGF2α were significantly higher in infertile patients compared with normozoospermic men." (PMID 29682163, 2018). "Statistically lower catalase activity was present in infertile subjects than that in the control ones (SMD = –1.91, 95% CI: –2.79, –1.04, Z = 4.28, p < 0.0001)." (PMID 29849956, 2018). "Previous studies involving various ethnicities in different geographical regions and countries have described the association between SNPs in the CAT, GPX, GST, NOS, NRF2, and SOD genes and infertility." (PMID 26618172, 2015). "Their study showed a significant elevation in intracellular activity of SOD and decreasing in catalase activity in infertile samples." (PMID 17540046, 2007). "However, the activity of SOD was higher in the infertile group, while for CAT, activity was greater in the healthy group." (PMID 35624681, 2022). "Also, seminal plasma levels of GPx, SOD, and CAT tend to be lower in infertile men compared to fertile controls." (PMID 35624681, 2022).
infertile (continued). "Moreover, in these groups, the decline in TAC was accompanied by a significant increase in catalase activity compared to values obtained for the fertile group (p < 0.01 for professional drivers and p < 0.001 for infertile men with varicocele)." (PMID 35270405, 2022). "Moreover, in obese and infertile women were observed higher levels of CAT activity, demonstrating that the follicular fluid of obese women was associated with a higher CAT activity indicating excessive oxidative stress." (PMID 34573073, 2021). "We could present further documents for supporting this hypothesis: altered expression of antioxidant genes NRF2, GPX4, SOD2, and CAT at mRNA levels are correlated to the greater risks of males' infertility." (PMID 34401649, 2021). "Therefore, this research aimed at the determination of the impact(s) of DPP on the levels of mRNA expression of antioxidant genes (NRF2, GPX4, SOD2, and CAT) in infertile male." (PMID 34401649, 2021). "The rise of CAT activity in semen of infertile patients with varicocele and leukocytospermia could be explained as a possible “chronic oxidative stress”." (PMID 31781347, 2019). "Mucuna administration increased testosterone and LH levels and decreased lipid peroxidation and FSH in infertile men also stimulated the antioxidant enzymes and hormones such as catalase, SOD and GSH via reactivating the antioxidant defense system and recovered sperm count and motility." (PMID 27561457, 2016). "Moreover, infertile patients with leukocytospermia or varicocele showed significantly reduced seminal concentrations of obestatin and ghrelin concomitant with increased levels of CAT, MDA, IL-6, and TNF-α with respect to those observed in the control group." (PMID 31781347, 2019). "The results obtained from our study clearly demonstrate that %DFI, protamine deficiency and MDA (lipid peroxidation) levels are significantly higher, whereas TAC, CAT and SOD are significantly lower, in infertile men compared to fertile men." (PMID 38255792, 2024). "Randomized clinical trials demonstrated that supplementation with omega-3 to males with infertility increased their antioxidant capacity as measured by the activity of superoxide dismutase (SOD) and catalase, as well as the seminal antioxidant capacity." (PMID 37977328, 2024). "In the context of endometriosis-related infertility, markers of oxidative stress, such as ROS, NO, and MDA, were significantly raised, while antioxidant markers TAC, SOD, catalase, GPx, and GR were all significantly lower." (PMID 37638130, 2023). "The in vivo antioxidants (SOD, CAT, and GSH) play a pivotal role in the reduction of oxidative stress and thus decrease the chances of infertility." (PMID 35814917, 2022). "Another study reported that the seminal plasma of infertile men presented higher SOD activity, while the CAT activity was similar to that of seminal plasma of fertile men." (PMID 34573073, 2021). "We also conclude that administering DPP in infertile males enhances the levels of expression of NRF2, GPX4, SOD2, and CAT genes and improves the semen quality including sperm count, semen volume, and morphology and motility of sperm." (PMID 34401649, 2021). "According to the findings, mRNA expression levels of antioxidant genes SOD2, GPX4, CAT and NRF2 are significantly lower in infertile case in comparison with the healthy control." (PMID 34401649, 2021). "A deeper comprehension of the mechanisms that are behind, as well as the effective role of the antioxidants, more particularly, SOD, CAT, and GPX activity, and how to manage them in reproduction could be a step ahead for the unexplained infertility couple." (PMID 34573073, 2021). "These enzymes were found suppressed in infertile groups of normozoospermics,normozoospermic cigarette smokers and normozoospermics under psychological stress by 18,23 and 24% for SOD, and 6, 2 and 26% for catalase, respectively." (PMID 19789214, 2009).
infertile (continued). "Furthermore, a controlled clinical trial demonstrated that the administration of 400 mg/kg of gelatinous capsules daily for 30 days by infertile men increased the expressions of Nrf2, glutathione peroxidase (GPx4), superoxide dismutase (SOD2), and catalase (CAT) genes." (PMID 38535326, 2024). "They showed antioxidant enzyme activities such as catalase, peroxidase, SOD, and GST were recovered after direct exposure of lycopene to the CPA‐treated (CPA + lycopene‐treated) infertile animals may be due to the potent antioxidant activity of lycopene either by rapid destruction of free radical." (PMID 34925809, 2021). "The results indicated that the activities of seminal enzymic antioxidants, such as catalase, GPX and GST, were remarkably decreased in infertility patients, and the concentrations of seminal non-enzymic antioxidants, such as GSH, VC and VE, were obviously lower in infertility patients." (PMID 29849956, 2018). "First, the heterogeneity among the studies of most analyzed markers (MDA, TAC, SOD, CAT, GPX, GSH, GST, VE) associated with infertility was modest (>50%) and could not be reduced lower than 50% neither by reasonable exclusion nor subgroup analysis (Data not shown)." (PMID 29849956, 2018). "In the infertile men not exposed to genital heat stress, the DFI index was negatively correlated with TAC, catalase activity, and SOD activity (p < 0.05 for all cases)." (PMID 35270405, 2022). "Despite the increased CAT activity in the semen of both groups of infertile patients, MDA levels were still elevated, suggesting that the CAT activity was not able to counteract the peroxide excess." (PMID 31781347, 2019).